GSK3B (glycogen synthase kinase 3 beta)
Diseases named in the same sentence as GSK3B in open-access papers (continued):
Sharing a sentence is not in itself a finding about the gene and the disease.
diabetic nephropathy (30 papers, 2012 to 2026). "Dysregulation of GSK3β has been associated with CKD such as diabetic nephropathy and glomerulosclerosis, where changes in cytoskeletal dynamics exacerbate disease progression." (PMID 40526103, 2025). "Insulin deficiency has been shown to result in decreased Ser9 phosphorylation of GSK3β and a resultant increase in GSK3β activity and has been implicated in the pathogenesis of diabetic nephropathy and retinopathy." (PMID 30978208, 2019). "The abnormal activatin of GSK-3β is associated with several kidney diseases, such as diabetic nephropathy, mesangioproliferative glomerulonephritis, lupus nephritis and chronic allograft nephropathy." (PMID 22243669, 2012). "This study aims to validate the molecular mechanism by which PCA regulates ERS via the GSK3β/Nrf2 pathway, offering novel therapeutic strategies for diabetic kidney disease." (PMID 41306290, 2025). "GSK3β dysregulation has been associated with various CKD, including glomerular disease, diabetic kidney disease (DKD), and chronic renal tubulointerstitial disease, in both human patients and preclinical models." (PMID 40526103, 2025). "Cultured podocytes with a higher DLX6-AS1 expression exhibited a damaged phenotype and inflammatory responses through the miR-346-mediated regulation of the GSK-3β pathway, contributing to the progression of diabetic nephropathy." (PMID 39595187, 2024). "LncRNA AK044604 (regulator of insulin sensitivity and autophagy, Risa) and autophagy-related factors Sirt1 and GSK3β play important roles in diabetic nephropathy (DN)." (PMID 35614465, 2022). "GSK-3β is a central regulator of proliferation, aging, apoptosis, and other physiological activities, and it also plays a key role in diabetic nephropathy." (PMID 33897769, 2021). "An in-depth study of GSK-3β helps to better understand the mechanism of diabetic nephropathy and provides new insights for the prevention and treatment of the disease." (PMID 33897769, 2021). "The expression and activity of GSK-3β in the renal tissue of patients with diabetic nephropathy have been reported to be significantly regulated." (PMID 33897769, 2021). "It is now well established from a variety of studies that GSK-3β in diabetic nephropathy mainly converge Wnt/β-catenin, PI3K/Akt/GSK-3β, epithelial–mesenchymal transition, etc." (PMID 33897769, 2021). "Another study also suggests that fenofibrate prevents the progress of diabetic nephropathy via activating the PI3K/Akt/GSK-3β/Nrf2 pathway." (PMID 32051732, 2020). "The present study suggests that Nrf2-HO-1 signaling has an inhibitory role in the regulation of EMT through the modulation of ROS-mediated PI3K/Akt/GSK-3β activity, highlighting Nrf2-HO-1 and GSK-3β as potential therapeutic targets in diabetic nephropathy." (PMID 31467925, 2019). "Consistent with these, the results of renal biopsy specimens from patients at different stages of diabetic nephropathy demonstrated a consistent increase in the expression of total and activated GSK3β in glomeruli and tubules, correlated with the severity of diabetic nephropathy." (PMID 40526103, 2025). "Moreover, based on previous studies, zinc supplementation has been demonstrated to modulate the PI3K/Akt/GSK-3β signaling pathway and impede the progression of renal interstitial fibrosis in diabetic nephropathy." (PMID 39028478, 2025). "However, in patients with diabetic nephropathy, lncRNA Dlx6-os1 expression increases, resulting in GSK-3β upregulation, thus leading to increased expression of inflammatory factors and cell damage-associated factors, podocyte injury, and albuminuria." (PMID 36854759, 2023). "In addition, diabetic kidney disease can be improved by β-hydroxybutyrate therapy by inhibiting glycogen synthase kinase-3 beta (GSK3β) and reactivating Nrf2 in glomerular podocytes." (PMID 37371607, 2023).
diabetic nephropathy (continued). "Resveratrol, triptolide, astragaloside IV, ginsenoside Rg1, and ferulic acid can exert their effects in the treatment of diabetic nephropathy through activation of miR-383-5p, ERK signaling, miR-141-3p/PTEN/Akt/mTOR pathway, and AKT/GSK3β/β-linked protein pathway-mediated autophagy, respectively." (PMID 37810881, 2023). "Our study assessed whether SAL exerts a protective effect on streptozotocin (STZ)-induced diabetic nephropathy (DN) in rats via the Akt/GSK-3β signalling pathway." (PMID 36086879, 2022). "A thorough understanding of GSK-3β is crucial to understand the mechanism of diabetic nephropathy." (PMID 33897769, 2021). "PCs appear to mitigate diabetic nephropathy by reducing MFG-E8 levels and modulating the ERK1/2, Akt, and GSK-3β pathways." (PMID 39995417, 2025). "PCs treatment reduced MFG-E8, phospho-ERK1/2, phospho-Akt, and phospho-GSK-3β levels in db/db mouse kidneys, indicating MFG-E8’s influence on the progression of diabetic nephropathy." (PMID 39995417, 2025). "GSK3b plays a key role in kidney injury across various diseases, including AKI, diabetic nephropathy and renal ageing." (PMID 40845179, 2025). "This article explores the changes in protein and phosphorylated protein in podocytes after GSK-3β knockdown to learn the influence affected by GSK-3β and probes new ways of preventing or treating diabetic nephropathy." (PMID 33897769, 2021). "Burgeoning evidence from our and other research groups indicates that GSK3β is overactive in various CKD, including chronic allograft nephropathy, obstructive nephropathy and diabetic nephropathy." (PMID 31349118, 2019). "The results showed that Schisandrin A had a protective effect on diabetic nephropathy, EGFR might be a potential therapeutic target, and AKT/GSK-3β might be involved in this process." (PMID 39194535, 2024). "Interestingly, GSK-3β was involved in both pathways, and it has been described to play a nonignorable role in several diseases, including diabetic nephropathy and glomerular podocyte injury." (PMID 36854759, 2023). "In the diabetic nephropathy mice experiment model, troglitazone a peroxisome proliferator -activated receptor gamma (PPAR gamma) agonists, ameliorate renal fibrotic lesions through reverse high glucose induced expressions of GSK-3β and inhibition epithelial-mesenchymal transition." (PMID 22243669, 2012).
nasopharyngeal carcinoma (29 papers, 2008 to 2025). A carcinoma arising from the nasopharyngeal epithelium. "In a study involving 188 patients with nasopharyngeal cancer the intensity of acute reaction occurred significantly more frequently in patients with one allelic variation of Wnt/β-catenin GSK3β (rs375557) gene and recessive variant of adenomatous polyposis coli gene (APC, rs454886) polymorphisms." (PMID 28401452, 2018). "Conversely, in nasopharyngeal carcinoma (NPC) PEDF expression suppresses NPC cell migration through the LRP6/GSK3β/β-catenin axis." (PMID 40001923, 2025). "It has also been reported that silencing NUSAP1 reduces the Wnt/β-catenin signaling pathway in nasopharyngeal cancer by downregulating phosphorylation of glycogen synthase kinase 3 beta (GSK-3β), reducing cell proliferation, and reducing invasion." (PMID 35710427, 2022). "In nasopharyngeal carcinoma cells, knockout of PLAC8 radiosensitizes nasopharyngeal carcinoma cells by activating the PI3K/AKT/GSK3β pathway." (PMID 34627411, 2021). "CXCL5 has been shown to activate ERK1/2 and PI3K/Akt signaling pathways in HCC cells by interacting with its receptor CXCR212 and activate the ERK/GSK-3β/snail signaling pathway in nasopharyngeal carcinoma cells." (PMID 32632106, 2020). "A recent study reported that GSK3β negatively regulates EZH2 expression in nasopharyngeal cancer cells, and the level of GSK3β phosphorylation at Ser9 is associated with higher EZH2 protein expression in patients with nasopharyngeal carcinoma." (PMID 27494834, 2016). "Upregulation of Bmi-1 also induces the epithelial-mesenchymal transition (EMT), enhances the aggressiveness of human nasopharyngeal carcinoma cells and stabilizes Snail, a transcriptional repressor associated with EMT, via modulation of the PI3K/Akt/GSK-3β pathway." (PMID 22967049, 2012). "We found that expression of EZH2 correlated with phosphorylated GSK3β (p-GSK3β) at Ser 9 (an inactivated form of GSK3β) in human nasopharyngeal carcinoma (NPC) samples." (PMID 23874688, 2013). "Research has shown that in nasopharyngeal carcinoma (NPC), the overexpression of NUSAP1 leads to increased phosphorylation of GSK-3B, thereby reducing its enzymatic activity." (PMID 40535133, 2025). "In nasopharyngeal carcinoma, CXCL5/CXCR2 axis promoted cell migration and invasion by inducing EMT through ERK/GSK-3β/Snail signalling pathway." (PMID 36151545, 2022). "UBE2T enhances nasopharyngeal carcinoma cell multiplication and invasion by activating the AKT/GSK3β/β-catenin pathway." (PMID 33934686, 2021). "Wogonin also induced nasopharyngeal carcinoma (NPC) cell apoptosis via inhibiting the activity of glycogen synthase kinase 3β (GSK-3β), a multifunctional serine/threonine kinase that was reported to inhibit apoptosis, and down-regulating the expression of ΔNp63, a survival factor in NPC cells." (PMID 28702078, 2017). "A study has shown that BMI1 inhibited the expression of PTEN, and modulated PI3K/AKT/GSK-3b/snail signaling, which promotes EMT and enhances the metastatic ability of nasopharyngeal cancer cells." (PMID 23820733, 2013). "In nasopharyngeal carcinoma, CXCL5 contributes to EMT by activating ERK/GSK-3β/Snail signaling." (PMID 35853880, 2022). "Interestingly, elevated UBE2T expression in nasopharyngeal carcinomas activates the AKT/GSK3β/β-catenin pathway, and inhibition of the pathway with the AKT inhibitor MK-2206 2HCL blocks the pro-metastatic effect of UBE2T in nasopharyngeal cancers cells." (PMID 27729585, 2016). "Furthermore, in nasopharyngeal carcinoma, PLAC8 contributes to radioresistance by inhibiting the PI3K/AKT/GSK3β pathway, as knockout of PLAC8 sensitizes nasopharyngeal carcinoma cells to radiation by activating the PI3K/AKT/GSK3β pathway." (PMID 31448883, 2019).
nasopharyngeal carcinoma (continued). "Interestingly, we noticed that the EZH2 amino acid sequence contains several glycogen synthase kinase 3 beta (GSK3β) phosphorylation motifs (Ser/Thr-X-X-X-Ser/Thr, where X represents any amino acid), and GSK3β and EZH2 interaction has been shown in nasopharyngeal cancer with unknown consequence." (PMID 27494834, 2016). "Contradicting the previous finding, we found that the levels of E-cadherin, β-catenin, Glycogen Synthase Kinase 3ß (GSK3β), axin and α-catenin were not affected by the expression of LMP1 sequences from normal B cells or nasopharyngeal carcinoma." (PMID 18806872, 2008).
esophageal squamous cell carcinoma (27 papers, 2015 to 2026). Esophageal squamous cell carcinoma (ESCC) is a type of esophageal carcinoma (EC) that can affect any part of the esophagus, but is usually located in the upper or middle third. "Among these, circGSK3β, derived from GSK3β, has been implicated in promoting cell proliferation, migration, and invasion in gastric, hepatocellular, and esophageal squamous cell carcinomas." (PMID 39366935, 2024). "It has been reported TDO2 controls M2 macrophages polarization to promote esophageal squamous cell carcinoma progression via AKT/GSK3b/IL‐8 signaling pathway,[14a] suggesting a correlation between TDO2 and suppression of inflammatory responses." (PMID 39364706, 2024). "Sterile alpha motif domain-containing protein 9 (SAMD9) promotes EMT and metastasis of esophageal squamous cell carcinoma by stimulating MYH9-mediated GSK3β/β-catenin signalling." (PMID 37875476, 2023). "Whereas STAT3 is not described as a direct substrate, inhibition of GSK3β after stimulation with IFN-γ, IL-6, or IFN-α reduces the phosphorylation of STAT3 on Y705, and GSK3β modifies STAT3 phosphorylation in esophageal squamous cell carcinoma." (PMID 31862381, 2020). "STAT3 is also a target of GSK3β and GSK3β inhibition reduced STAT3 phosphorylation while higher GSK3β expression promoted esophageal squamous cell carcinoma progression through STAT3 in vitro and in vivo." (PMID 31696055, 2019). "Activating the Notch1 signaling pathway, which depends on GSK3β/β-catenin, inhibited cell proliferation and induced apoptosis in the human esophageal squamous cell carcinoma cell line EC9706." (PMID 26563263, 2015). "Overexpression of LncRNA maternally expressed gene 3 (MEG3) could downregulate PSAT1 and suppress the activation of GSK-3β/Snail signaling pathway in esophageal squamous cell carcinoma (ESCC)." (PMID 37127605, 2023). "In esophageal squamous cell carcinoma (ESCC), MIF drives cancer progression via Akt activation and GSK3β tumor suppressor inactivation." (PMID 38732068, 2024). "Interestingly, lncRNA MEG3 exerts tumor-suppressive effects and inhibits Epithelial-mesenchymal transition (EMT) by suppressing the PSAT1-dependent GSK3β/Snail signaling pathway in esophageal squamous cell carcinoma (ESCC)." (PMID 37147729, 2023). "In esophageal squamous cell carcinoma, FSCN1 was reported to promote tumor progression by the AKT/GSK3β signaling pathway." (PMID 37491232, 2023). "Esophageal squamous cell carcinoma (ESCC) is a very aggressive cancer, and the ΔNp63α/RSK4/GSK-3β axis (RSK4: ribosomal protein S6 kinase A6; GSK: glycogen synthase kinase 3β) plays a pivotal role in radioresistance in ESCC." (PMID 36140189, 2022). "In esophageal squamous cell carcinoma, TOPK was positively correlated with tumor metastasis by activating Src/GSK3β/STAT3 signaling pathway." (PMID 33842463, 2021). "For example, LUCAT1 can promote esophageal squamous cell carcinoma and clear cell renal cell carcinoma tumorigenesis by controlling the ubiquitination and stability of DNMT1 and the AKT/GSK-3β signaling pathway, respectively." (PMID 33097685, 2020). "In addition to GSK3β-mediated β-catenin regulation, AURKA also directly binds β-catenin in esophageal squamous cell carcinoma (ESCC) cells." (PMID 39334449, 2024). "Another interesting study suggests that circGSK3β, directly interacts with GSK3β and inhibits GSK3β activity, thereby protecting β-catenin from phosphorylation and degradation which subsequently results in promoting β-catenin pathway and EMT in esophageal squamous cell carcinoma (ESCC)." (PMID 36114510, 2022).
acute myeloid leukemia (26 papers, 2009 to 2025). Acute myeloid leukemia (AML) is a group of neoplasms arising from precursor cells committed to the myeloid cell-line differentiation. "Loss of cytotoxicity and defective metabolism are linked to glycogen synthase kinase 3 beta (GSK3β) overexpression in natural killer (NK) cells from patients with acute myeloid leukemia or from healthy donors after expansion ex vivo with IL-15." (PMID 36765663, 2023). "GSK3β inhibitors suppress cell growth and induce apoptosis in different leukemia cell lines including acute myeloid leukemia (AML)." (PMID 33672232, 2021). "A major observation is that leukemic stem cells (CD34+ CD38- CD123+, acute myeloid leukemia) surviving through the GSK3β pathway are from female patients." (PMID 33498808, 2021). "Recently, two groups showed that GSK3β inhibition in normal peripheral NK cells enhances their cytotoxic effects against acute myeloid leukemia (AML) cells." (PMID 32503133, 2020). "Recent studies have shown that nuclear localization of GSK3β is regulated by mTOR complex 1 (mTORC1), and nuclear GSK3β facilitates acute myeloid leukemia (AML) cell growth and drug resistance." (PMID 32158616, 2020). "Actually, the downregulation of Mcl-1 through GSK3β activation contributed to As2O3-induced apoptosis in acute myeloid leukemia." (PMID 31121982, 2019). "Mcl-1 is known as a crucial component in As2O3-induced apoptosis through GSK3β activation in acute myeloid leukemia." (PMID 31121982, 2019). "Most studies have focused on the role of total GSK-3 or GSK-3β, but recent studies implicated the oncogenic role of GSK-3α in acute myeloid leukemia (AML), prostate cancer, and pancreatic cancer." (PMID 27049759, 2016). "It has been reported that downregulation of Mcl-1 through GSK-3β activation contributes to chemically-induced apoptosis in acute myeloid leukemia cells." (PMID 24585095, 2014). "Our findings are supported by another study showing that GSK-3β positively regulates NF-κB-mediated chemoresistance in acute myeloid leukaemia." (PMID 19920820, 2009). "Similarly, pharmacologic or genetic inactivation of GSK-3β restores the cytotoxicity of NK cells against acute myeloid leukemia (AML) cells, suggesting the benefit of GSK-3 inhibition in leukemia treatment." (PMID 33918810, 2021). "Recent evidence suggests that GSK3α and GSK3β play distinct roles in sperm motility and fertility, amyloid production in the brain, cortical development, atherosclerosis development, and acute myeloid leukemia development." (PMID 34394077, 2021). "Results from preclinical studies suggest that isoform-targeted inhibition of macrophage GSK3α or GSK3β may be effective in the treatment of acute myeloid leukemia and atherosclerosis." (PMID 33672232, 2021). "In acute myeloid leukemia, the FLT3 gene (which encodes a class III receptor tyrosine kinase that regulates hematopoiesis) is frequently mutated, and FLT3-mutant cells are able to promote the Wnt/β-catenin pathway by activating Integrin αvβ3/PI3K/Akt/GSK-3β signaling." (PMID 37445628, 2023). "Recently, it has been demonstrated that GSK-3β positively regulates NF-κB-mediated drug resistance in acute myeloid leukemia (AML)." (PMID 21110852, 2010). "Tivantinib is reported as a more prominent GSK3α and GSK3β inhibitor and a weak MET inhibitor in acute myeloid leukemia." (PMID 39458991, 2024). "As far as GSK3β inhibitors are concerned, LY2090314 is currently under investigation in a phase II trial of refractory/recurrent acute myeloid leukemia (clinicaltrials.gov identifier NCT01214603)." (PMID 29593255, 2018). "In summary, our study have found miR-302a enhance the sensitivity of acute myeloid leukemia cell lines to VP-16 by targeting Rad52 and in part via the AKT/Gsk-3β/β-catenin signaling cascade." (PMID 29088754, 2017).
acute myeloid leukemia (continued). "Natural killer (NK) cells from patients with acute myeloid leukemia (AML), or from healthy donors and expanded with IL-15, show defective cytotoxicity and elevated levels of glycogen synthase kinase 3 beta (GSK3β), and drug inhibition of GSK3β was able to improve their cytotoxicity and maturation." (PMID 36765663, 2023). "However, other acute myeloid leukemia subsets do not depend on GSK3β to survive and are capable to transform their microenvironment in a leukemic niche with benefits for their development." (PMID 33498808, 2021). "In conditional mouse knockout studies, deletion of GSK-3β expression was postulated to be necessary for the establishment of myelodysplastic disease syndrome (MDS) while both GSK-3β and GSK-3α were shown to be necessary for progression to acute myeloid leukemia (AML)." (PMID 32365809, 2020). "For example, in acute myeloid leukemia (AML), GSK3α but not GSK3β suppresses c-myc and cyclin D1 to maintain stemness." (PMID 41300341, 2025).